SLC27A2 (solute carrier family 27 member 2)
Diseases named in the same sentence as SLC27A2 in open-access papers (continued):
Sharing a sentence is not in itself a finding about the gene and the disease.
nonalcoholic fatty liver disease (4 papers, 2020 to 2024). "In recent years, studies have found that SLC27A2 plays an important role in maintaining intracellular lipid balance, as well as in non-alcoholic fatty liver disease and renal fibrosis." (PMID 38664735, 2024).
ovarian carcinoma (4 papers, 2020 to 2025). A malignant neoplasm originating from the surface ovarian epithelium. "Meanwhile, SLC27A2 has also been found to be associated with the progression of ovarian cancer and renal clear cell carcinoma." (PMID 38664735, 2024). "In ovarian cancer, SLC27A2 regulates a microRNA that targets a drug efflux pump, influencing cisplatin resistance." (PMID 40647532, 2025). "In endometrial and ovarian cancer, researchers found that SLC27A2 can play a biological role in regulating chemical resistance." (PMID 33029112, 2020).
colorectal cancer (3 papers, 2022 to 2025). A primary or metastatic malignant neoplasm that affects the colon or rectum. "For example, SLC27A2 is upregulated in colorectal cancer, impacts FAO, and interacts with PPARs, impacting crucial signaling pathways." (PMID 40647532, 2025). "This study aims to explore the mechanisms of how PPARs and SLC27A2 regulate FA metabolism in colorectal cancer (CRC) and find new strategies for CRC treatment." (PMID 37041476, 2023). "Consistently, the expression of SLC27A2 in colorectal cancer tissues was also higher to paired para-cancerous tissues in our ongoing study." (PMID 37041476, 2023). "The whole transcriptome sequencing showed that the increased expression of SLC27A2 can lead to the downregulation of CDK3, and it has been reported that CDK3 promotes the EMT process in colorectal cancer." (PMID 35927229, 2022).
glioblastoma (3 papers, 2023 to 2025). The most malignant astrocytic tumor (WHO grade IV). "SLC27A2 expression was significantly lower in primary tumors than in normal tissues in glioblastomas, cutaneous melanomas, and HNSQ." (PMID 38719806, 2024). "GEPIA analyses also show that the level of SLC27A2 expression is about 200 times lower in glioblastoma than among other SLC27 genes." (PMID 37239243, 2023). "This is supported by the lack of association between the level of SLC27A2 expression in glioblastoma tumors and patient prognosis." (PMID 37239243, 2023). "In glioblastoma, the altered expression of SLC27 family proteins, including SLC27A2, affects fatty acid uptake and utilization." (PMID 40647532, 2025). "Furthermore, the low expression of SLC27A2 in glioblastoma tumors suggests that it does not play a significant role in the tumorigenesis processes in glioblastoma." (PMID 37239243, 2023).
renal carcinoma (3 papers, 2022 to 2023). A carcinoma arising from the epithelium of the renal parenchyma or the renal pelvis. "In summary, SLC27A2 overexpression inhibited ccRCC EMT in vitro while the knockdown of SLC27A2 in renal cancer cells promoted ccRCC EMT in vitro." (PMID 35927229, 2022). "SLC27A2-overexpressing lentivirus and SLC27A2 small interfering RNA (siRNA) were transfected into relevant cell lines to generate renal cancer cells with high SLC27A2 expression and low SLC27A2 expression (786-O and Caki)." (PMID 35927229, 2022). "Upregulation of SLC27A2 significantly inhibited the migration and invasion abilities of renal cancer cells 786-O and CAKI." (PMID 35927229, 2022). "SLC27A2 small interfering RNA was used to transfect renal cancer cells and down-regulate CDK3 expression in mRNA and protein." (PMID 35927229, 2022). "In this article, we verified the low expression level of SLC27A2 in both cell lines and renal cancer tissues." (PMID 35927229, 2022). "SLC27A2 was significantly downregulated in clinical specimens and renal cancer cell lines and predicted poor prognosis." (PMID 35927229, 2022). "Solute carrier family 27 member 2 (SLC27A2) suppresses renal cancer ability by down-regulating EMT." (PMID 37962768, 2023). "However, opposite results are reported by Xu and colleagues, which highlighted that SLC27A2 was downregulated in both renal cancer cell lines and tissues suggesting its correlation with favorable OS." (PMID 37397501, 2023). "Moreover, we knocked down the expression of SLC27A2 using siRNA in renal cancer cells and observed the opposite changes of EMT markers." (PMID 35927229, 2022). "We found that specific upregulation of SLC27A2 could significantly inhibited the proliferation, migration, and invasion of renal cancer cell lines." (PMID 35927229, 2022). "SLC27A2 could also influence the Epithelial-mesenchymal transition (EMT) signaling pathway, linked to the progression and metastasis of renal cancer." (PMID 35927229, 2022). "As a result, we speculated that SLC27A2 might take part in the migration and invasion of renal cancer cell by coordinating CDK3-mediated EMT in ccRCC." (PMID 35927229, 2022). "We also verified the regulatory effect of SLC27A2 on CDK3 using qRT-PCR and western blot in two renal cancer cells." (PMID 35927229, 2022). "However, the relationship between SLC27A2 and EMT in renal cancer has not been explored." (PMID 35927229, 2022).
clear cell renal cell carcinoma (2 papers, 2024 to 2025). "This study investigated the expression of HEAT repeat-containing protein 1 (HEATR1) and solute carrier family 27 member 2 (SLC27A2) in clear cell renal cell carcinoma (ccRCC)." (PMID 40647532, 2025).
differentiated thyroid carcinoma (2 papers, 2022 to 2025). Differentiated thyroid carcinoma (DTC), also known as papillary or follicular thyroid carcinoma, is a slow-growing malignancy usually presenting in adults as an asymptomatic thyroid mass. "The oncogenic role of SLC27A2 was demonstrated in differentiated thyroid cancer and acute lymphoblastic leukemia." (PMID 41373732, 2025).
endometrial carcinoma (2 papers, 2019 to 2025). A malignant tumor arising from the epithelium that lines the cavity of the uterine body. "In endometrial cancer, SLC27A2 is downregulated by FOXM1, affecting fatty acid metabolism and disease progression." (PMID 40647532, 2025).
lymphoma (2 papers, 2022 to 2024). A malignant (clonal) proliferation of B- lymphocytes or T- lymphocytes which involves the lymph nodes, bone marrow and/or extranodal sites. "Overall, we demonstrated that malignant tumors with low SLC27A2/FATP2 expression, such as EBV-positive lymphomas, acquire resistance to ferroptosis owing to a limited influx of exogenous AA, resulting in low intracellular AA levels despite high extracellular AA levels." (PMID 38719806, 2024).
neuroendocrine tumors (2 papers, 2013 to 2022). "Indeed, this gene was reported to regulate the tumor suppressor gene PARP and decreased SLC27A2 expression levels were found in the metastatic compared to the non-metastatic neuroendocrine tumors." (PMID 23282137, 2013). "SLC27A2 has been reported to regulate the tumor suppressor gene PARP, with reduced levels of SLC27A2 expression in metastatic tumors compared to non-metastatic neuroendocrine tumors." (PMID 36324578, 2022).
non-small cell lung carcinoma (2 papers, 2024 to 2025). A group of at least three distinct histological types of lung cancer, including non-small cell squamous cell carcinoma, adenocarcinoma, and large cell carcinoma. "SLC27A2 regulates non-small-cell lung cancer and kidney fibrosis through its effect on lipid metabolism." (PMID 40510178, 2025).
renal cell carcinoma (2 papers, 2022 to 2025). "Expression of SLC27A2 was found to be context-dependent based on its tumor-suppressive role in renal cell carcinoma." (PMID 41373732, 2025). "The results confirmed that the protein level of epithelial cell marker E-cadherin in renal cell carcinoma cell lines was up-regulated when SLC27A2 was overexpressed." (PMID 35927229, 2022). "SLC27A2 was discovered to be downregulated in renal cell carcinoma tissues and cell lines, which matches numerous prior results from other cancer types." (PMID 35927229, 2022). "However, there are few studies on the expression of SLC27A2 and its biological behavior in renal cell carcinoma." (PMID 35927229, 2022). "In contrast, the mesenchymal cell markers N-cadherin, Vimentin, and Snail were down-regulated when overexpressing SLC27A2, suggesting that the EMT process is inhibited during renal cell carcinoma progression." (PMID 35927229, 2022).
breast tumors (1 paper, 2013). "The expression levels and subcellular localization of the CCNB2, ASPM, CDCA7, KIAA0101, and SLC27A2 proteins were measured using immunohistochemistry (IHC) on a panel of 80 primary invasive breast tumors." (PMID 23282137, 2013).
ciliopathies (1 paper, 2025). "GO analysis revealed that SLC27A2+ EpCs were enriched in genes associated with ‘ciliopathies’, ‘fatty acid metabolism’, ‘lymphocyte-mediated immunity’ and ‘arachidonic acid metabolic process’ pathways." (PMID 40195539, 2025). "Our findings suggest that SLC27A2 expression is primarily localized in goblet and ciliated cell types and that SLC27A2+ EpCs may be associated with imbalanced lipid and fatty acid metabolism, ciliopathies and inflammatory responses." (PMID 40195539, 2025).
demyelinating disorder (1 paper, 2025). "In the neurological context, it has been suggested that impaired SLC27A2 activity leads to the accumulation of saturated very-long-chain fatty acids in a demyelinating disorder X-adrenoleukodystrophy (MIM: 300100)." (PMID 40510178, 2025).
gastric cancer (1 paper, 2015). A primary or metastatic malignant neoplasm involving the stomach. "PPAR signaling network (left) showed alterations of fatty acid uptake (SLC27A2/6) and transports (FABP1-6) in gastric cancers, leading to dysregulated activation of PPAR pathways, resulting in alteration of PPAR targets involved in lipid homeostasis." (PMID 26657352, 2015).
hyperthyroidism (1 paper, 2022). Overactivity of the thyroid gland resulting in overproduction of thyroid hormone and increased metabolic rate. "Our results suggest that EEP attenuates hyperthyroidism-induced oxidative stress via the PPAR and AMPK pathways, with the main targets of action being by influencing the expression of FABP and HMGCR at the protein level and by affecting the expression of EHHADH, HMGCR, and SLC27A2 at the mRNA level." (PMID 36613632, 2022).
kidney cancer (1 paper, 2022). Primary or metastatic malignant neoplasm involving the kidney. "In our study, we found MAP7, SLC16A12, and SLC27A2 in kidney cancer cells when compared with normal kidney cells, which agreed with the results of the TCGA-KIRC." (PMID 36620592, 2022).
kidney damage (1 paper, 2020). "Recently, study has shown that SLC27A2 ablation can restore FAO-related key enzymes activity caused by kidney damage, and protect TECs from lipotoxicity." (PMID 33219209, 2020).
nasal polyp (1 paper, 2025). "A comprehensive study of patient tissue samples revealed the fatty acid transporter FATP2, encoded by the SLC27A2 gene, in nasal polyp epithelium." (PMID 40195539, 2025). "Integrated analysis of bulk and single-cell RNA sequencing data reveals upregulation of SLC27A2/FATP2 in nasal polyp epithelium, which correlates with increased lipid peroxidation." (PMID 40195539, 2025).
prostate carcinoma (1 paper, 2025). A carcinoma that arises from epithelial cells of the prostate gland. "Immunohistochemical information from the HPA database showed that higher staining of GSTM4, PLP1, and PTGS2 was found in normal prostate tissue, while higher staining of SLC27A2, SLC45A3, APOE, and ABCC4 was observed in prostate cancer tissue." (PMID 40861808, 2025).
tumor (88 papers, 2009 to 2026). "More recent in vivo evidence showed that genetic deletion of the SLC27A2 gene (also known as FATP2) encoding the very long-chain acyl-CoA synthetase, specifically in neutrophils using the S100a8-cre mice, abrogated tumor growth in different tumor models." (PMID 31616408, 2019). "IHC analysis in an independent cohort of ccRCC patients, including those with high-grade disease, demonstrated that both HEATR1 and SLC27A2 are expressed in tumor tissues." (PMID 40647532, 2025). "Recent research has revealed that SLC27A2 influences intracellular lipid homeostasis and plays a vital role in type 2 diabetes, renal fibrogenesis, and tumor progression." (PMID 40647532, 2025). "HEATR1 was expressed in the cytoplasm and nucleus, while SLC27A2 was expressed in the cell membrane of the tumor cells." (PMID 40647532, 2025). "Four of these genes were significantly upregulated in tumor tissues (p < 0.0001 for all comparisons): SLC27A2, TXNDC16, TBL1XR1, and GDAP1." (PMID 41373732, 2025). "In a subcutaneous xenograft model of tumor cells tested so far, the expression of SLC27A2 regulated their viability and tumor size." (PMID 38719806, 2024). "Accumulation of lipid peroxides, as assessed by Liperfluo, a pattern similar to that of the subcutaneous tumor tissue with B95-8 cells, was observed in SLC27A2 tumor tissue." (PMID 38719806, 2024). "After 5 weeks, the viability and size of the SLC27A2 tumor tissues were significantly lower than those of the empty tissues." (PMID 38719806, 2024). "Studies have demonstrated that inhibiting the upregulation of SLC27A2 in polymorphonuclear myeloid-derived suppressor cells can weaken their immunosuppressive effects and inhibit tumor progression." (PMID 38753091, 2024). "In line with this, chemotactic lipid mediators, such as 12-HETE, 20-HETE, and 12-HHTrE were increased in SLC27A2-overexpressing tumor tissues." (PMID 38719806, 2024). "Altogether, these results suggest that the overexpression of SLC27A2 suppress tumor growth by the accumulation of lipid peroxides." (PMID 38719806, 2024). "As a novel target for cancer research and treatment, further exploration of SLC27A2 expression in immune cells within the tumor immune microenvironment is warranted." (PMID 38753091, 2024). "SLC27A2 exhibits a critical function not only in BC cells but also in shaping the tumor microenvironment." (PMID 38753091, 2024). "Subsequent experiments validated that reducing SLC27A2 expression in BC cell lines or using the SLC27A2 inhibitor, Lipofermata, effectively inhibited tumor growth." (PMID 38753091, 2024). "Downregulation of SLC27A2, encoding FATP2, reduced tumor burden, and exerted a synergistic effect in preventing tumor progression in different NB mouse models when combined with conventional chemotherapeutic drugs." (PMID 39101440, 2024). "Both knockdown of SLC27A2 and Lipofermata treatment delayed the growth of tumors, reflected in the tumor volume and tumor weight." (PMID 38753091, 2024). "To evaluate the diagnostic utility of SLC27A2, we performed receiver operating characteristic (ROC) curve analysis by comparing the mRNA levels of SLC27A2 between DTC tumor tissues and adjacent normal tissues." (PMID 34854499, 2022). "Our results show that SLC27A2 plays an important role in tumor proliferation and migration, providing a new putative target for the diagnosis and treatment of TC." (PMID 34854499, 2022). "The results showed that the staining strength of SLC27A2 was significantly higher in tumor tissues (p < 0.05) than that in the adjacent normal tissues." (PMID 34854499, 2022). "In the last few years, it has been found that SLC27A2 not only affects intracellular lipid homeostasis but also plays an important role in type 2 diabetes, renal fibrogenesis, and tumor progression." (PMID 34854499, 2022).
tumor (continued). "Inhibiting FA uptake by targeting SLC27A2 blocked tumor growth, prolonged animal survival, and enhanced the efficacy of conventional chemotherapy in multiple preclinical NB models." (PMID 35764645, 2022). "Silencing SLC27A2 significantly reduced tumor growth (assessed by MRI imaging, p = 0.048) and tumor weights (p = 0.01)." (PMID 35764645, 2022). "Results from experiments with a variety of tumor model mice suggest that SLC27A2‐specific inhibitors slow tumor growth and that the combined use of immune checkpoint inhibitors can help eliminate tumors." (PMID 34854499, 2022). "The results showed that SLC27A1 and SLC27A3 were higher-expressed in tumor samples of both sets, while SLC27A2, SLC27A4, and SLC27A5 expressions were much lower." (PMID 35927229, 2022). "The full body deletion of the FATP2-encoding gene slc27a2, or the PMN-specific deletion of this gene, led to an enhanced level of tumor rejection in mice." (PMID 34831183, 2021). "FA transport protein 2 (FATP2, encoded by the Slc27a2 gene) was found to be upregulated exclusively in PMN-MDSCs of tumour-bearing mice and increased lipid accumulation in PMN-MDSCs." (PMID 34722305, 2021). "Due to loss of biopsy cores, insufficient tumor cells present in the cores or affluence of necrotic tissue, 72/80 FFPE specimens were evaluated for CCNB2, KIAA0101, SLC27A2, ASPM, and CDCA7 immunostaining." (PMID 23282137, 2013). "In ccRCC, strategies could involve enhancing or re-establishing SLC27A2 function to normalize altered fatty acid metabolism within tumor cells." (PMID 40647532, 2025). "Targeting SLC27A2 could disrupt fatty acid metabolism, potentially inhibiting tumor growth and improving patient outcomes." (PMID 40647532, 2025). "Consequently, SLC27A2 emerges as an outstanding therapeutic target for regulating tumor growth across various malignant cell types." (PMID 38753091, 2024). "In addition, patients with low expression of SLC27A2 had poor prognosis, and cell experiments confirmed that low expression of SLC27A2 promoted tumor cell cycle progression and inhibited cell apoptosis." (PMID 38664735, 2024). "We calculated the AA/18:1 ratio in the phospholipids of tumor tissues, since oleic acid (18:1) has been recently reported to have an inhibitory effect on ferroptosis induction, which showed that the ratio was higher in SLC27A2 tumors." (PMID 38719806, 2024). "Moreover, SLC27A2 was ectopically expressed in SLC27A2low tumor cell lines, which were predicted to be poor prognostic by in silico analysis." (PMID 38719806, 2024). "Therefore, the abnormal expression of SLC27A2 leads to abnormal fatty acid metabolism in patients, thereby promoting the progression of tumor cell cycle and inhibiting cell apoptosis." (PMID 38664735, 2024). "Lipidomic analysis of these tumor tissues showed a significant increase in the free AA ratio as well as in arachidonoyl-phosphatidylcholine (PC) and -phosphatidylethanolamine (PE) per tumor cell in SLC27A2 mice." (PMID 38719806, 2024). "Morphologically, the control tumor tissues showed a significant accumulation of lipids just below the capsule, where many tumor cells had infiltrated, whereas SLC27A2 tumor tissues were filled with F4/80-positive inflammatory cells and only a few, if any, tumor cells." (PMID 38719806, 2024). "One possible interpretation of these results is that AA, a precursor of pro-inflammatory lipid mediators, may be decreased owing to the low expression of SLC27A2 in tumor cells, followed by a failure to induce an appropriate anti-tumor immune response." (PMID 38719806, 2024). "Therefore, SLC27A2 is mainly involved in fatty acid related pathways in the pathological mechanism of DLBCL Tumor cell immune response and cell cycle related pathways." (PMID 38664735, 2024). "Combined with checkpoint inhibitors, SLC27A2 inhibition blocked tumor progression in mice." (PMID 36869083, 2023).